LINC02304 (long independently transcribed non-coding RNA 2304)
Gene: Long non-coding RNA gene on chromosome 14 (97,154,634 to 97,219,421, forward strand). Ensembl gene ENSG00000259110.
Gene Ontology:
Biological process: SRP-dependent cotranslational protein targeting to membrane, signal sequence recognition
Cellular component: signal recognition particle, endoplasmic reticulum targeting